S100A7 (S100 calcium binding protein A7)
Diseases named in the same sentence as S100A7 in open-access papers (continued):
Sharing a sentence is not in itself a finding about the gene and the disease.
tumor (continued). "Specifically, the level 3 classifier shows strong correlations among genes like KRT5, S100A7, KRT16, S100P, and LY6D, while the level 6 classifier exhibits similar patterns with GPR17, RGR, and NPPA, highlighting the complex interplay of genes in tumor subtype classification." (PMID 40802546, 2025). "In various pre-clinical mouse models including the S100A7 overexpression bi-transgenic and Hu-PDX mouse models, we showed that inhibition of S100A7/cPLA2 signaling by using small molecule inhibitor against cPLA2 significantly reduced tumor burden and metastasis." (PMID 35135586, 2022). "In addition to classical tumor‐related pathways, many immune‐related signaling pathways were also enriched among the genes that were differentially expressed between wild‐type ESCC cells and S100A7‐overexpressing ESCC cells." (PMID 34323409, 2021). "While other members of this family, such as S100A4, S100A7 and S100A13, have been shown to participate under similar conditions, this discussion focuses on S100A8/A9's role in tumorigenesis by reviewing the effects of S100A8/A9 on tumor cells or vascular endothelial cells." (PMID 22685372, 2012). "Therefore, unlike in other tumors, our data suggests S100A7 to be a tumor suppressor in OSCC." (PMID 19691830, 2009). "As S100A5, S100A7, S100A7A, S100Z, TCHHL1, and S100G are ubiquitously expressed at low levels in both tumor and paratumor samples, they were not included in the following analyses." (PMID 37133437, 2023). "We also discovered an increased expression of S100A7 and low level of TLR4 in late‐stage tumors with or without DSS as compared to early‐stage tumor lesions." (PMID 33969603, 2022). "For tumor tissues lacking normal tissues matched as controls in the TIMER2 web server, we evaluated the alteration of S100A7 between the normal controls from the GTEx dataset and cancer samples from TCGA." (PMID 35205150, 2022). "Furthermore, we also observed that the degree of negative correlation was increased, when we reanalyzed S100A7 and TLR4 expression only in malignant tumor tissues." (PMID 33969603, 2022).
cancer (71 papers, 2010 to 2025). A tumor composed of atypical neoplastic, often pleomorphic cells that invade other tissues. "S100A7, also known as psoriasin, is an EF-hand calcium-binding protein implicated in tumorigenesis and cancer progression." (PMID 41256331, 2025). "Copy number variation was similar between the two groups pan-cancer, but single nucleotide variation was associated with S100A7 expression." (PMID 38499391, 2024). "Lines of evidence have proved that S100A7 as a potential diagnostic and prognostic biomarker contributes to the malignancy of carcinomas via crosstalk and promoting angiogenesis." (PMID 37543645, 2023). "Aberrant S100A7 expression has been associated with a number of cancers, including breast, head and neck, prostate, lung and skin cancers." (PMID 35205150, 2022). "Herein, the potential association between the immune cell infiltration and S100A7 gene expression in diverse TCGA cancers was analyzed with various algorithms, including TIMER, CIBERSORT, CIBERSORT-ABS, QUANTISEQ, XCELL, MCPCOUNTER and EPIC." (PMID 35205150, 2022). "Emerging data have implicated the importance of S100A7 in the pathogenesis of various human disorders, including cancers." (PMID 34323409, 2021). "Overexpression of S100A7 is found in high-risk dysplastic oral lesions linked to cancer development." (PMID 34359370, 2021). "Exploration of the underlying molecular mechanisms demonstrated that intracellular S100A7 binds to JAB1 to promote the activation of the cancer‐associated AKT, ERK, and NF‐kB signaling pathways, thereby promoting ESCC progression." (PMID 34323409, 2021). "The signaling pathways regulated by S100A7 are widely involved in local invasion and distant metastasis, which are one of the 10 hallmarks of cancer and a major cause of cancer‐related death." (PMID 34323409, 2021). "Cytoplasmic S100A7 overexpression is distinct from other protein biomarkers as the most significant candidate marker associated with cancer development in dysplastic lesions." (PMID 34359370, 2021). "Altered S100A7 expression has been linked to poor clinical outcomes in several solid cancer types by promoting invasiveness of cancer cells via upregulation of MMPs56." (PMID 33277602, 2020). "S100A7 or psoriasin was increased in local PDAC but correlated positively with SMI; thus, despite some evidence of association with cancer severity, S100A7 appears uninformative in this context." (PMID 33334063, 2020). "S100A7 has been suggested to be implicated in a variety of biologic events closely related to tumorigenesis and cancer progression." (PMID 28212564, 2017). "S100A7 expression can serve as a biomarker for identifying dysplastic lesions at high risk of cancer development." (PMID 28212564, 2017). "Up-regulation of S100A7 (Psoriasin), a small calcium-binding protein, is associated with the development of several types of carcinomas, but its function and possibility to serve as a diagnostic or prognostic marker have not been fully defined." (PMID 22082027, 2011). "Besides AGEs and HMGB1, S100 group of proteins like S100A4 and S100A7 are also implicated in cancer growth, migration and angiogenesis via potent interaction with RAGE and potential re-modelling of tumour micro-milieu." (PMID 37970208, 2023). "In addition, we showed the correlation between S100A7 expression and the immune infiltration level of cancer-associated fibroblasts in different tumors." (PMID 35205150, 2022). "The evidence suggested that the S100A7 level was associated with prognosis in different cancers." (PMID 35205150, 2022). "In addition, although we observed a significant differential expression of S100A7 between pathological stages in various tumors, the specific association between the S100A7 expression level and cancer pathological stages still requires further investigation." (PMID 35205150, 2022).
cancer (continued). "We therefore further examined the roles of S100A7 using immunohistochemistry to analyze its association with clinicopathological parameters, in addition to its potential association with S100A7 inducers and downstream oncogenic pathways involved in carcinoma–ASC interactions." (PMID 28629450, 2017). "Moreover, we found a positive correlation between S100A7 expression and the estimated infiltration value of cancer-associated fibroblasts in the TCGA cancers of BRCA-LumA, BRCA-LumB, and LUAD; however, S100A7 expression was negatively correlated in CESC, HNSC, HNSC-HPV-, and STAD." (PMID 35205150, 2022). "Upregulated S100A7 promotes cancer cell proliferation and migration through intracellular attachment to JAB1 as well as secretion and activation of RAGE receptors." (PMID 41164825, 2025). "Upregulation of S100A7 protein has been predicted in cancer from several tissues (oral, esophagus, and breast) or serum with a strong correlation to poor prognosis." (PMID 41164825, 2025). "GSEA showed that S100A7 was related to multiple cancer development pathways, such as Notch signaling." (PMID 38499391, 2024). "An abnormal expression of S100A7 has been observed in various cancers, including up-regulation in the tissues and blood of ESCC patients." (PMID 38791062, 2024). "Overall, we discovered that S100A7 was closely related to various biological activities, such as the cell cycle, metabolism of various substances, and cancer development." (PMID 38499391, 2024). "S100A7 was also correlated with the expression of programmed cell death-ligand-1 in multiple types of cancer." (PMID 38499391, 2024). "In this study, we first established the level of S100A7 expression pan-cancer and its relationship with patient prognosis." (PMID 38499391, 2024). "Multiple methods were used to assess the correlation between immune cell infiltration and S100A7 expression pan-cancer." (PMID 38499391, 2024). "Survival analyses were performed to explore the relationship between S100A7 expression and pan-cancer prognosis." (PMID 38499391, 2024). "Spearman’s correlation analysis showed that S100A7 was closely related to immunomodulators pan-cancer." (PMID 38499391, 2024). "A recent pan-cancer study identified KRT16 as one of the proteins with the highest correlation in expression with S100A7." (PMID 38892279, 2024). "S100A7 was associated with B cells, CD4+ T cells, CD8+ T cells, cancer-associated fibroblasts, macrophages, neutrophils, and mast cells." (PMID 38499391, 2024). "S100A7 is downregulated in adjacent invasive cancer tissues; however, once the expression persists, the nuclear translocation of psoriasin is related to a poor clinical prognosis." (PMID 36235175, 2022). "A new therapeutic strategy is the use of neutralizing monoclonal antibodies against S100A7 in the treatment of cancer." (PMID 36235175, 2022). "Recent clinical data show that the copy number of the chromosomal region containing S100A genes, including S100A7, is amplified in cancer stem cells of TNBC and basal subtypes." (PMID 35135586, 2022). "The current pancancer study offers a relatively integrative understanding of the carcinogenic involvement of S100A7 in numerous types of cancers." (PMID 35205150, 2022). "Several studies have described a crucial role for intracellular and extracellular S100A7 in certain cancers; nevertheless, the function and mechanism of S100A7 in ESCC remain uncharted territory." (PMID 34323409, 2021). "StraticyteTM, the single protein biomarker S100A7, was able to make a 5-year prediction of the probability of dysplastic lesions progressing to cancer." (PMID 34359370, 2021). "Although many studies have reported the biological functions and molecular mechanisms of S100 proteins in specific cancers, the role of S100A7 in ESCC remains poorly understood." (PMID 34323409, 2021).
cancer (continued). "Based on the Oncomine database, there are no obvious distinctions in S100A1, S100A4, S100A5, S100A6, and S100A13 expressions between cancer tissues and normal colon mucosa, and S100A7, S100A12, and S100Z are slightly overexpressed in CRC tissues." (PMID 33294444, 2020). "S100A8/9 and CXCL1/2, or S100A7/8/9 and IRAK1, form a feedback loop to cause cancer chemoresistance and drive breast cancer tumor sphere growth." (PMID 32547883, 2020). "The mRNA expression of inflammatory cytokines, S100A7/8/9 and cancer stem cell (CSC)-related genes were examined by qPCR." (PMID 32547883, 2020). "Based on these results, we suggest that Src/Stat3/S100A7 signaling contributes to the metastasis of cancer cells through the EMT pathway." (PMID 31731716, 2019). "A wound-healing assay was used to investigate the effects of S100A7 on the migration of cancer cells after treatment with Lu, Qu, Su6656, and S3I-201." (PMID 31731716, 2019). "To investigate the regulatory signaling of S100A7 in the metastasis of cancer cells, we analyzed the 5′-upstream regions of s100a7 gene and found one Stat-binding site." (PMID 31731716, 2019). "To further analyze the regulation signaling of S100A7 in cancer cells, we isolated the 5′-upstream regions of S100A7 as promoter and cloned it to the pGL3-Basic vector, creating the pGL3-S100A7-Luc plasmid." (PMID 31731716, 2019). "Several lines of evidence demonstrated that S100A7 is involved in the regulation of cell proliferation, migration, invasion, angiogenesis and metastasis of numerous malignant tumors." (PMID 28212564, 2017). "To further explore a role of S100A7 expression in carcinoma–ASC interaction, we examined the proliferation and migration rates of MCF7, SK-BR-3, T47D, and ZR-75-1 cells stimulated by ASC-derived factors by suppressing S100A7 expression." (PMID 28629450, 2017). "In summary, our findings prove a novel function of the Hippo-YAP pathway in regulation of S100A7 expression in A431 cells and provide a novel strategy for S100A7-regualted cancer therapy." (PMID 27203549, 2016). "S100A7 was first found overexpressed in psoriatic scales, but further studies have demonstrated that a variety of inflammatory dermatoses and cancers actually exhibited up-regulated an S100A7 expression." (PMID 26633653, 2015). "For example, S100A4, S100A6, S100A7 and S100B play oncogenic roles in cancer development, whereasS100B, S100A2, and S100A11 are believed as TSGs." (PMID 23894350, 2013). "S100A7 promotes cancer cell migration and contributes to the aggressive phenotype." (PMID 38473906, 2024). "Next, we identified the relationship between S100A7 expression and pan-cancer prognosis." (PMID 38499391, 2024). "This study showed that S100A7 was closely related to methylation in multiple types of cancer, suggesting that it may play an important role in executing this modification." (PMID 38499391, 2024). "However, the downregulation of S100A7 protein and its dual functionality in cancers were also reported." (PMID 38473906, 2024). "In this study, we first explored the pan-cancer differences in S100A7 expression." (PMID 38499391, 2024). "We also studied the relationship between methylation and S100A7 expression in cancer." (PMID 38499391, 2024). "S100A7 was related to the expression of programmed cell death-ligand-1 in multiple types of cancer." (PMID 38499391, 2024). "Fourth, when the HCC cases were categorized according to cancer pathological grade, high mRNA expression of S100A7 in pathological grades II and III correlated with shorter OS, as did high expression of S100A9 in pathological grade II and of S100A10 in pathological grade III." (PMID 39128058, 2024).
cancer (continued). "What`s more, the regulatory effects of S100A7 on immunomodulators, immune activity, and infiltration could vary across different types of cancer." (PMID 38499391, 2024). "We also explored the relationship between S100A7 expression and pan-cancer prognosis." (PMID 38499391, 2024). "We performed in vitro experiments to verify the functions of S100A7 in cancer." (PMID 38499391, 2024). "We found that S100A7 was related to the prognosis of multiple types of cancer." (PMID 38499391, 2024). "S100A7 is related to the progression of multiple types of cancer." (PMID 38499391, 2024). "Therefore, we thoroughly evaluated the S100A7 gene in various types of cancers according to the TCGA, CPTAC and GEO databases and its molecular features, genetic alteration, or DNA methylation." (PMID 35205150, 2022). "In addition, S100A7 levels were associated with the infiltration level of CD8+ T cells and cancer-associated fibroblasts in different tumors." (PMID 35205150, 2022). "Therefore, we investigated the potential oncogenic roles of S100A7 across 33 tumors based on datasets from The Cancer Genome Atlas (TCGA) and Gene Expression Omnibus (GEO)." (PMID 35205150, 2022). "Furthermore, using the MEXPRESS approach, we investigated the potential correlation between S100A7 DNA methylation and the pathogenesis of TCGA cancers." (PMID 35205150, 2022). "In BC_sBRCA1 we observed overexpression of S100A7 (psoriasin), a DNA damage-inducible gene associated with poor outcome in estrogen negative cancers, meanwhile indicating a good response to etoposide." (PMID 33525353, 2021). "S100A7 overexpression has been reported in several cancers, including OSCC." (PMID 32334479, 2020). "Activation of RAGE by S100A4, S100A7, S100A8, S100A9, S100A14, S100B, and S100P was associated with upregulation of NF-κB that induced progression of different types of cancer including pancreatic, melanoma, breast, prostate, colon, neuroblastoma, and esophageal." (PMID 32443845, 2020). "In this study, we found that S100A7 was highly expressed in cancer cells and could be reduced by luteolin (Lu) and quercetin (Qu) through Src/Stat3 signaling." (PMID 31731716, 2019). "Understanding the regulation signaling of S100A7 in cancer cells might provide a way of developing new therapeutic strategies." (PMID 31731716, 2019). "We speculated that one possible factor was whether endogenous S100A7 was expressed in a cell line, which could primarily depend on the final differentiation state acquired by the cancer cell line." (PMID 28177901, 2017). "However, further investigation is required to elucidate the relationship between S100A7 and ER status with regard to cancer–ASC interaction." (PMID 28629450, 2017). "The results of the 2D invasion assay and S100A7 immunostaining also indicated that ASCs adjacent to the carcinoma cells could promote S100A7 expression." (PMID 28629450, 2017). "Comprehensive microarray analysis in our study revealed that S100A7 (psoriasin) could be a potent regulatory gene involved in the carcinoma–ASC interaction." (PMID 28629450, 2017). "In particular, S100A4, S100A6, S100A7 and S100A10 have been found to be overexpressed in some cancer types, and could be associated with aggressive cancer phenotype." (PMID 27008379, 2016). "However, when analysing the mean plasma S100A7 autoantibody levels of cancer patients versus those with benign ovarian disease, only patients with advanced cancer had higher mean S100A7 autoantibody levels." (PMID 21339995, 2011). "Therefore, S100A7 seems to play an important role in the progression of multiple types of cancer." (PMID 38499391, 2024). "Finally, correlation analysis showed that S100A7 was related to immune checkpoints pan-cancer." (PMID 38499391, 2024).